IL1B (interleukin 1 beta)
Diseases named in the same sentence as IL1B in open-access papers (continued):
Sharing a sentence is not in itself a finding about the gene and the disease.
COVID-19 (continued). "Across all the soluble proinflammatory markers we examined, ICAM, IL-1β, IL-4, IL-6, TNFα, and Syndecan showed a statistically significant positive correlation between cytokine or epithelial marker and antibody quantity regardless of COVID-19 disease severity." (PMID 36865568, 2022). "The retrospective analysis included serum cytokines (interleukins; IL-1β, IL-6, IL-8 and tumour necrosis factor (TNFα)) measured using EllaTM (Bio-Techne, Oxford, UK) and PCT measured by Roche Cobas (Burgess Hill, UK) in patients admitted with COVID-19 between March 2020 and January 2021." (PMID 35500008, 2022). "Interestingly, IDO1 inhibitors suppress the COVID-19-induced pro-inflammatory cytokine release, including TNF-α, IL-6, IL-1α and IL-1β in isolated PBMCs derived from COVID-19-infected rhesus macaques and lower mortality among critically ill patients with COVID-19." (PMID 36589459, 2022). "In addition, the S protein can drive the formation of NLRP3 inflammatory bodies in macrophages of COVID-19 patients and induce them to secrete mature IL-1β, but this does not occur in macrophages of healthy volunteers." (PMID 36389144, 2022). "Notably, the cytokines that we investigated are normally expressed in human tissue; in particular, as shown by our data, IL-1β, IL-6, and IFN-β are constitutively basally expressed in control cases, while IFN-λ is more expressed in control lung tissue and downregulated in COVID-19 patients’ lungs." (PMID 36422642, 2022). "Moreover, classical monocytes from severe COVID-19 patients displayed a type I IFN response together with the TNF/IL-1β-mediated inflammation, being absent in mild COVID-19 patients." (PMID 35663932, 2022). "Traditionally, activation of the NLRP3 inflammasone is regarded to be the main inducer of pathogenic pro-inflammatory cytokines IL-1β, IL-18 and IL-6 during COVID-19, but it has become clear that multiple non-conical pathways can contribute and indeed become the dominate inducers of IL-1β." (PMID 35244141, 2022). "Importantly, stimulation of AIM2 responses in PBMCs obtained from both non-fibrotic or fibrotic PC patients, did not induce increases of IL-1β, a cytokine which is elevated in COVID-19 and correlates with disease symptoms." (PMID 35844548, 2022). "Following preincubation for 1 h of PBMC with the extract, a significant inhibition of IL-1β, TNF, and IL-6 was observed at a concentration of 5 or 10 μg/mL, with a similar potency when compared to 1 μM dexamethasone, the current reference treatment for COVID-19." (PMID 35455990, 2022). "Indeed, an increase in cytokines such as TNF-α, MCP-1, IL-6, IL-1β, and IL-10 was shown in the rat ARDS model induced by LPS administration, which corresponds to the cytokine profile of patients with a severe form of COVID-19." (PMID 36290634, 2022). "Our results showed that serum IL-1β levels were not elevated in severe COVID-19 patients compared to nonsevere patients (P = 0.33), while levels of IL-1β were elevated in nonsurvivor COVID-19 patients compared to survivors (WMD = 0.20, 95% CI: 0.15-0.24, and P < 0.01)." (PMID 35540724, 2022). "According to previously published data, IL-1β was not always increased in severe COVID-19 cases, but was significantly lower in asymptomatic cases than in symptomatic patients, suggesting IL-1β levels may be predictors of clinical symptoms." (PMID 36012146, 2022). "Doxycycline (a tetracycline) reduces IL-6, IL-1β and TNF-α levels, however, doxycycline treatment did not have a significant clinical impact on time to recovery, hospital admissions or deaths related to COVID-19 in patients with high risk to adverse outcomes." (PMID 35720378, 2022). "However, platelets from critically ill COVID-19 patients do not secrete higher levels of IL-1β than control platelets when cultured overnight." (PMID 35842415, 2022).
COVID-19 (continued). "Importantly, strong increase in PGE2 and in IL-6/IL-8/IL-1β cytokines was observed in monocytes activated with DD in the presence of IC of PVCoV-2 coated with plasma from hospitalized COVID-19 patients but not from healthy donors." (PMID 35385545, 2022). "In patients infected with SARS-CoV-2, higher levels of the proinflammatory cytokines IL-1β, IL-6, IL-8, IL-13, IL-17, RANTES, and IFN-γ were found, and these increased cytokines and chemokines mediated the infection immunopathogenesis and played important roles in the progression of COVID-19." (PMID 35893674, 2022). "However, serum TNF-α, IL-1β, IL-6, and blood-bacteria-free DNA were not different between healthy control and mild COVID-19 cases." (PMID 35406667, 2022). "It is known that cytokine storm in COVID-19 consists of various, not necessarily overlapping, soluble immune mediators (SIMs) including IL-1β, IL-6, IL-8, and tumor necrosis factor-alpha (TNF-α) which could yield different predictive value." (PMID 33918563, 2021). "In addition, the hyperinflammatory state in COVID-19 is reported to resemble some aspects of hemophagocytic lymphohistiocytosis (HLH), a condition that may benefit from therapeutic IL-1β blockade." (PMID 33319166, 2021). "By contrast, the dynamic of MIP-1β, IL-1β, MIP-1α and IFN-γ showed a different profile during the follow up, with significant higher levels at month 1 (IL-1β and IFN-γ) and month 3 (MIP-1β, IL-1β, MIP-1α and IFN-γ) among patients with mild/moderate diseases, compared to those with severe COVID-19." (PMID 34835384, 2021). "IHC showed that high levels of IL-6 and IL-1β could be observed in the spleens and the LNs from COVID-19 autopsies, whereas, sections from trauma victims were absent of IL-6 and IL-1β expression." (PMID 33995382, 2021). "Additionally, in non-severe COVID-19—although significantly lower than severe ones—blood-cytokine levels (for example IL-1β, IL-1RA, IL-2R, IL-6, IL-7, IL-8, IL-9, IL-10, IFN-γ, TNF-α, G-CSF, GM-CSF, IP10, MCP1), can be increased." (PMID 34572585, 2021). "TH17 cells have a major role in inducing the proinflammatory effects of cytokines (G-CSF, IL1B, IL6, and TNF) and chemokines (KC, MIP2A, IL8, IP10, MIP3A) through secretion of inerleukin-17 (IL17), thus contributing to the cytokine storm and subsequent ARDS in COVID-19 patients." (PMID 34975885, 2021). "According to other studies, doxycycline may delay COVID-19 progression via anti-inflammatory activities, including regulating the NFκB pathway and inhibition of proinflammatory cytokine levels (IL-6, IL-1β, TNFα), measured during ARDS in severely ill COVID-19 patients." (PMID 34372498, 2021). "Particularly, the CRS-related cytokines, including IL-6, IL-1β, IL-10, IL-18, and IFN-γ, displayed progressive increase along disease severity from healthy controls to mild and severe patients, highlighting the broad and strong inflammatory responses in severe COVID-19 patients." (PMID 33712622, 2021). "In this regard, a clinical trial performed on COVID-19 patients indicated the ability of a nanomicellar form of CUR to significantly decrease the mRNA expression and cytokine secretion levels of IL-6 and IL-1β, which may ameliorate disease's clinical manifestation and promote overall recovery." (PMID 34584616, 2021). "However, transcriptional modules to quantify IL-1β or IL-6 response have not been used in COVID-19 to quantify the bioactivity of these cytokine pathways in vivo." (PMID 33319166, 2021). "Specifically, we found that the expression of genes encoding proinflammatory cytokines (IL12B, IL15, IL6, IL12A and IL1B) and chemokines (CXCL9, CXCL11 and CXCL10) was broadly increased in COVID-19 patients and speculate that other viral infections may also induce expression of these genes." (PMID 33780352, 2021).
COVID-19 (continued). "The highly activated M1 macrophage cluster showed predominant enrichment of pro-inflammatory mediators, including IL1B and CXCL8, which was further supported by our results showing that the highly activated M1 was highly enriched with gene sets from severe COVID-19 patients." (PMID 34315893, 2021). "In the milder stage of COVID-19, a positive correlation was detected between IL-33 and IL-1β, IL-12 and IL-23, while a stronger positive correlation between the serum values of IL-33 and TNF-α, IL-1β, IL-6, and IL-12 and IL-23 was detected in patients with COVID-19 with severe disease." (PMID 34917631, 2021). "Additionally, IL-1β, IL-6, and IL-8 were significantly upregulated in the critical COVID-19 non-survival group compared to the survival group." (PMID 34276659, 2021). "TCs have shown great potential for the management of COVID-19 through inhibition of SARS-CoV-2–induced hyperinflammation and cytokine storm, since TCs downregulate the production of inflammatory cytokines, including interleukins (IL-6, IL-33, and IL-1β) and tumor necrosis factor (TNF)-α." (PMID 33967777, 2021). "However, not all studies have shown an IL-1β elevation among COVID-19 patients, therefore, the importance of this interleukin in post-COVID depression requires more investigation." (PMID 34575258, 2021). "A significant increasing trend of IL-1β, IL-1ra, IL-2, IL-4, IL-5, IL-6, IL-7, IL-8, IL-10, IL-12(p70), IL-15, IL-17, FGF-b, G-CSF, GM-CSF, IFN-γ, IP-10, MCP-1, MIP-1α, PDGF, TNF-α, and VEGF was observed in the three groups (Controls ≤ Mild COVID-19 ≤ Severe COVID-19)." (PMID 34675240, 2021). "The generation of cytokine storm within COVID-19 patients required increased levels of IFN-γ and IL-1β that could stimulate the cellular response of T helper type 1 (Th1) which has a crucial function in the acceleration of specific immunity against COVID-19 outbreak." (PMID 32822430, 2020). "Pre-acquired gene polymorphism of IL-1β or IFN-γ genes in COVID-19 patients and superinfection by Acinetobacter baumannii in elderly COVID-19 patients may raise the chances of death irrespective of known co-morbidities." (PMID 33634060, 2020). "Despite the pulmonary injury, the production of pro-inflammatory cytokines including IL-1β, IL-6, TNF-α, macrophage inflammatory protein 1-α, interferon gamma-induced protein-10, and monocyte chemoattractant protein-1 were significantly enhanced in COVID-19 patients." (PMID 33041827, 2020). "Similarly, a more pronounced expression of type I IFN in mild COVID-19 patients and lack of IL1B mRNA levels increase were also confirmed in a recent study that analyzed by scRNA-seq two independent large cohorts of COVID-19 patients." (PMID 33129318, 2020). "Notably, cytokines such as TNF-α, IL-1β, IL-6, IFN-γ, and IL-10 not only amplify the production of additional cytokines—including themselves—but also play critical roles in regulating immune cell differentiation and function, thereby exacerbating immune dysregulation in severe COVID-19." (PMID 41596316, 2026). "Due to the attenuated immune response of COVID-19 patients, particularly the reduced upregulation of monocyte CD80 expression and the suppressed release of key cytokines such as IL-6, TNF, IL-1a, and IL-1b, this may lead to a decreased ability to clear C. albicans in these patients." (PMID 38658823, 2024). "Therefore, IL-1β may not be a key cytokine in the pathoetiology of patients first time contracting COVID-19." (PMID 38133713, 2024). "Furthermore, while systemic increases in IL-1β, IL-6, TNF-α, and IFN-γ have traditionally been viewed as immunopathological hallmarks of acute COVID-19, most of these cytokines, along with several markers of brain injuries, have recently emerged as potential biochemical indicators of long COVID-19." (PMID 38338174, 2024).
COVID-19 (continued). "SARS-CoV-2 infection could trigger the activation of NLRP3 inflammasome to release IL-1β, IL-18, and gasdermin D and, consequently, damage to lung tissue in patients with COVID-19, suggesting the dysregulation of NLRP3 inflammasome might contribute to the severity of COVID-19." (PMID 36960050, 2023). "Consequently, several drugs/compounds targeting IL-1β or IL-6 have been evaluated in several phase 3 clinical trials each (NCT04372186, NCT04409262, NCT04678739, NCT04364009, NCT04443881 and NCT04324021) as therapeutic option of SARS-CoV-2 infection to treat or prevent severe COVID-19 evaluated." (PMID 36941580, 2023). "The severity of COVID-19 is often accompanied by IFN-Is response, in addition to the TNF/IL-1β response, indicating that the IFN-I response could aggravate the hyper-inflammatory response by strengthening TNF/IL-1β-driven inflammation, thus influencing the severe progression of COVID-19." (PMID 38124132, 2023). "First, we studied the circulating levels of IL-1α, IL-1β, IL-18, IL-15, IL-12p40, IL-12p70, IL-6, IL-27, IL-1Ra, IL-1RI, IL-1RII, IL-6R and sgp130, which are innate proinflammatory cytokines, and their receptors in survivors and non-survivors of severe COVID-19 and healthy controls." (PMID 36142255, 2022). "However, the inflammatory response in COVID-19 still shares some common signatures with the inflammatory response in LPS-induced RAW264.7 cells, among which the most typical are TLR4, NF-κB, and other signaling pathways and their corresponding cytokines (including IL-6, TNF, IL-1β, etc.)." (PMID 35669076, 2022). "In module 2, mono-CD14+ cells in patients with severe COVID-19 exhibited higher expression levels of glycolysis-related genes (LDHA and PKM) and PPP-related genes (PGD and TKT), which may be involved in the proinflammatory response (upregulation of S100A8, S100A9, S100A12, and IL1B)." (PMID 33936072, 2021). "We believe that targeting the central pathway (IL-1β, TNF-α, IL-6), balancing the Th1 and Th2 response, and administering long-term anti-inflammatory therapy might be promising prospects to reduce cardiovascular impairment and even MODS during the acute and recovery phases of COVID-19." (PMID 32426374, 2020). "A strong relationship was observed between certain inflammatory markers, including IL-1β, IL-2, IFN-β, IFN-γ, IL-17, and GM-CSF, as well as several metabolites, particularly in COVID-19 non-survivors, such as LysoPCs, 3-hydroxykynurenine, and serotonin." (PMID 41002992, 2025). "Severe SARS-CoV-2 infection induces aberrant innate immune activation with elevated IL-6, IL-1β, TNF-α, and other soluble mediators; this hyperinflammatory state is a potent nonspecific mechanism of multi-organ injury in severe COVID-19." (PMID 41462971, 2025). "Both IL-1β and VEGF-A have been described as broadly elevated in hospitalized COVID-19 patients, irrespective of ICU level of care." (PMID 39763770, 2025). "In contrast, in COVID-19 patients, ACBP plasma concentrations correlated with the neutrophil/lymphocyte ratio, CRP and IL-6 but not IL-1β and IL-8." (PMID 39835130, 2024). "The serum IL-6, IL-1β, and TNF-α expression levels were measured by RT-PCR in COVID-19 patients (n = 41), stratified into non-survivors (n = 23) and survivors (n = 18), and in the serum of subjects in the control group (n = 20)." (PMID 39201618, 2024). "In univariable analyses, individuals with PASC tended to have lower levels of sCD14, IL10, IL17, IL1β, IL6 and TNFα compared to participants without PASC at 9–12 weeks after COVID-19 onset." (PMID 39008486, 2024). "Because comparing viral+ and viral− cells did not reveal viral-intrinsic effects on IL1B or IL18 expression, we examined proinflammatory cytokine expression across all clusters in the integrated (COVID-19-infected and control) human BALF data set." (PMID 37737611, 2023).
COVID-19 (continued). "The strength of our study lies in the comprehensive dynamics of the pro-inflammatory (mainly IL-1β, IL-6, IL-8, TNF-α) and anti-inflammatory (IL-10) cytokines over time and their comparison with non-severe COVID-19 cases as supporting evidence." (PMID 37384050, 2023). "For instance, IL1B, NFKB1, NLRP3, PYCARD, and CASP1 are listed in the COVID-19 Disease Map, while there are molecules absent from it, including CCL3, 3L1, 4L2, CXCL1, 2, 3, 5, 16, TNFAIP6, C15orf48, TMEM176A/B, NFE2, PADI4, RAB20, ETS2, PHLDA2, FOLR3, and HP." (PMID 37719701, 2023). "Compared with patients with COVID-19 but without fibrosis, the levels of IL-1β and TGF-α in post-COVID-19 patients with fibrosis were higher." (PMID 37601070, 2023). "High levels of CCL3 and IL1B mRNA were observed in the SEV and MOD groups compared to the CTRL, indicating that these mediators of COVID-19 inflammation are not sufficiently responsive to glucocorticoid treatment." (PMID 36993968, 2023). "Severe COVID-19 patients that developed AKI had increased levels of proinflammatory cytokines (e.g., IFN-γ, IL-1β, IL-8 and TNF-α) compared with non-severe patients." (PMID 37251383, 2023). "Patients with COVID-19 also display selective induction of the macrophages that produce IL-6, but not TNF-α and IL-1β, and this then directly promotes lymphocyte necrosis." (PMID 35464491, 2022). "Here, we show that human monocytes exposed to IC of SARS CoV-2 pseudovirus with plasma from COVID-19 patients but not from healthy subjects, produce PGE2 and IL-6, IL-8, and IL-1β cytokines only in the presence of soluble DD." (PMID 35385545, 2022). "COVID-19 ICU patients had significantly higher levels of the proinflammatory cytokines CXCL1, IL-1β, IL-6, MCP-1, and TNF-α compared to the non-COVID group." (PMID 35502320, 2022). "Systems biology studies have shown that proinflammatory cytokines, IL-6, IL-1β, and TNF-α, originating from SARS-CoV-2 infected lungs, but not from the peripheral blood cells, contribute to COVID-19 severity." (PMID 36298628, 2022). "With the exception of IL-1β and TNF-α, HIV/COVID-19 patients showed similar levels of IL-6 and IL-8 than those observed in HIV patients without COVID-19." (PMID 35891555, 2022). "Additionally, the concentrations of IL-1β (1,236.5 ± 398.1; p = 0.0105), IL-6 (1,408.9 ± 490.3; p = 0.0198), and IL-8 (1,443.4 ± 195.8; p = 0.0012) were significantly upregulated in the critical COVID-19 non-survival group compared to the critical COVID-19 survival group." (PMID 34276659, 2021). "We found that the serum levels of multiple pro-inflammatory cytokines or biomarkers, including IL-6, IL-10, IL-8, TNF-α, IL-1β, IL-2R, ferritin, hs-CRP and procalcitonin were substantially elevated in non-survivors with COVID-19." (PMID 34521370, 2021). "The levels of IL1-β, IL-6, IL-8 (p < 0.0001, for each), and TNF-α (p < 0.01) were significantly higher in the critical COVID-19 patients than in the mild COVID-19 and non-COVID-19 healthy controls." (PMID 34276659, 2021). "In conclusion, we showed an increase in the serum levels of cytokines, including IL1-β, IL-6, IL-8, and TNF-α in ICU patients relative to mild COVID-19, while RANTES serum levels were increased in the mild, not ICU patients." (PMID 34276659, 2021). "In classical monocytes from patients with severe COVID-19, type I IFN response co-existed with the TNF/IL-1β-driven inflammation, and this was not seen in patients with milder COVID-19." (PMID 32651212, 2020). "Most COVID-19 patients had either no elevation or only mild increases in the major proinflammatory cytokines including TNF-α, IL-1α, IL-1β, IFN-ɣ, etc.." (PMID 32687484, 2020). "We conclude that the observed upregulation of IL1B, CXCL8 and CCL3 in week 2 compared to the later time points is attributable to interindividual patient differences rather than a general feature of convalescent COVID-19 patients." (PMID 38391913, 2024).